CALB2 (calbindin 2)
Description:
Calcium-binding protein involved in calcium homeostasis and signal transduction. It plays a critical role in buffering intracellular calcium levels and modulating calcium-dependent signaling pathways. Predominantly expressed in specific neuronal populations, influences synaptic plasticity and neuronal excitability, contributing to learning and memory (By similarity). During embryonic development, it facilitates neuronal differentiation and maturation (By similarity).
Synonyms: CR; CAB29; CAL2
Tractability: PROTAC: its protein half-life has been measured.
Gene: Protein-coding gene on chromosome 16 (71,358,713 to 71,390,436, forward strand). Ensembl gene ENSG00000172137.
Subcellular location: Synapse; Cell projection, dendrite
Subcellular location (Human Protein Atlas): Cytosol
Gene Ontology:
Molecular function: calcium ion binding; calcium ion binding involved in regulation of presynaptic cytosolic calcium ion concentration
Biological process: intracellular calcium ion homeostasis; regulation of synaptic plasticity; synaptic signaling; regulation of presynaptic cytosolic calcium ion concentration
Cellular component: cytosol; dendriole; dendrite; nucleus; parallel fiber to Purkinje cell synapse; synapse; terminal bouton; cuticular plate; gap junction; stereocilium
Genetic constraint (gnomAD): Loss-of-function variants: 27 observed, 38.88 expected, observed/expected ratio (o/e) 0.69, 90% interval 0.51 to 0.96. The upper end of that interval is the gene's LOEUF score, 0.96, which puts it in group 4 of 6, group 1 being the genes least tolerant of losing a copy. Missense variants: 306 observed, 299.8 expected, observed/expected ratio (o/e) 1.02, 90% interval 0.93 to 1.12. Synonymous variants: 127 observed, 121.86 expected, observed/expected ratio (o/e) 1.04, 90% interval 0.9 to 1.21.
Homologues: Orthologues: chimpanzee CALB2 (99% identical), rat Calb2 (99% identical), guinea pig CALB2 (99% identical), mouse Calb2 (99% identical), dog CALB2 (98% identical), pig CALB2 (97% identical), rabbit CALB2 (97% identical), macaque CALB2 (93% identical), tropical clawed frog calb2 (82% identical), zebrafish calb2a (77% identical), zebrafish calb2b (72% identical), Drosophila melanogaster Cbp53E (44% identical). Paralogues in human: CALB1 (57% identical), SCGN (39% identical).
Diseases named in the same sentence as CALB2 in open-access papers:
CALB2 is named in the same sentence as 50 diseases in open-access papers, as found by Europe PMC text mining. Sharing a sentence is not in itself a finding about the gene and the disease. The quoted sentences say what the papers report.
mesothelioma (11 papers, 2009 to 2025). A usually malignant and aggressive neoplasm of the mesothelium which is often associated with exposure to asbestos. "CALB2 has been proposed as a diagnostic marker for some human diseases, including Hirschsprung disease and some cancers, such as mesothelioma and lung tumours." (PMID 28158993, 2017). "Further studies demonstrated that CALB2 was specifically expressed in CRC and mesotheliomas, which was considered as well as the diagnostic biomarker for CRC and mesotheliomas." (PMID 37664836, 2023). "Since we observed an about 30-fold difference in CALB2 promoter activity between the different mesothelioma cell lines, we can reasonably assume that the difference is not due to differential expression of the normalizer." (PMID 26848772, 2016). "This is consistent with the previously defined minimal mouse Calb2 promoter (−115/+54bp) shown to be active in rat cortical neuronal cells, rat cerebellar granule cells, colon adenocarcinoma (WiDr) and mesothelioma cells (SPC111)." (PMID 26848772, 2016). "The −161/+80bp fragment of the CALB2 promoter was identified as the minimal element resulting in sustained transcriptional activity in all tested mesothelioma cell lines." (PMID 26848772, 2016). "We further characterized a stretch of~1 kb (−835/+80bp) of the human CALB2 promoter by creating four different 5′-deletion promoter reporter constructs and testing their activity in four different mesothelioma cell lines." (PMID 26848772, 2016). "This study provides the first insight in the regulation of CALB2 expression in mesothelioma cells." (PMID 26848772, 2016). "Moreover, the methylation status of nine CpG sites in the CALB2 promoter of epithelioid (n = 57) and biphasic (n = 23) mesothelioma samples from The Cancer Genome Atlas (TCGA) database generally showed low methylation levels, particularly at CpG sites nearest to the TSS." (PMID 26848772, 2016). "By real time PCR we found that our cell lines expressed high mRNA levels of typical mesothelioma markers as mesothelin (MSLN) and calretinin (CALB2), and of BMI-1, a stemness marker, and DKK1, a potent Wingless [WNT] inhibitor." (PMID 20175889, 2010). "Employing a reporter plasmid assay, where the 573-nt stretch of the CALB2-3′UTR was inserted downstream of the Firefly luciferase reporter, we observed that CALB2-3′UTR affected the reporter mRNA stability, as it downregulated the reporter expression in mesothelioma cells." (PMID 28611824, 2017). "Additionally, a bipartite butyrate-responsive element in the human CALB2 promoter was found to act as a repressor element upon butyrate treatment in colon carcinoma but not in mesothelioma cells." (PMID 26848772, 2016). "Additionally, we did not observe differential methylation status of CALB2 promoter between epithelioid and biphasic mesothelioma in tumors from TCGA database or a strong negative correlation of promoter methylation with gene expression." (PMID 26848772, 2016). "Thus altered DNA methylation of the CALB2 promoter is very likely not responsible for the differences in calretinin expression levels between low-expressing biphasic/sarcomatoid and high-expressing epithelioid mesothelioma cells." (PMID 26848772, 2016).
colon carcinoma (9 papers, 2014 to 2024). "In colon cancer tissues, the expression level of CALB2 was significantly higher than that of normal colon epithelial cells, and at the same time, the expression level of CALB2 was positively correlated with the metastasis of local lymph nodes and other organs." (PMID 38742936, 2024). "Additionally, a number of studies have shown that CALB2 promotes the generation and development of various cancer cells, including colon cancer and pancreatic cancer, and is closely related to cancer cell migration." (PMID 37031243, 2023). "Finally, we verified the clinical significance of CALB2 expression and its role to promote the invasion and migration of colon cancer cells in vitro." (PMID 37497410, 2023). "CALB2 is expressed in most poorly differentiated colon carcinomas." (PMID 36275690, 2022). "It is also found that CALB2 may serve as a mediator for cell apoptosis in 5-FU-treated colon cancer through the mitochondrial pathway." (PMID 34381786, 2021). "In addition, several transcripts exist from the human CALB2 gene, which are present in several colon cancer cell lines and in tumor tissue from primary colon tumors." (PMID 24550787, 2014). "Analysis of the human CALB2 promoter region revealed additional putative BRE elements named BRE7–13 upstream of the previously identified region that contains 2 functional BRE (BRE5–6), which act as transcriptional repressors in colon cancer cells." (PMID 29699512, 2018).
colorectal cancer (5 papers, 2011 to 2026). A primary or metastatic malignant neoplasm that affects the colon or rectum. "CALB2 is a calcium binding protein, has been identified playing an important role in regulating the response of colorectal cancer to 5-Fluorouracil." (PMID 35963640, 2022). "CALB2 has been shown to regulate colorectal cancer patient sensitivity to 5-fluorouracil by modulating the intrinsic apoptosis pathway." (PMID 33563317, 2021). "The role of the calcium binding protein, Calbindin 2 (CALB2), in regulating the response of colorectal cancer (CRC) cells to 5-Fluorouracil (5-FU) was investigated." (PMID 21629658, 2011). "CALB2 and C5orf23 (NPR3) are each involved in one clinical trial related to colorectal cancer." (PMID 39484215, 2024).
hepatocellular carcinoma (5 papers, 2022 to 2026). A malignant tumor that arises from hepatocytes. "CALB2 has been proposed to promote hepatocellular carcinoma metastasis via the TRPV2-Ca2+-ERK1/2 signaling pathway." (PMID 39358777, 2024). "It has been reported that CALB2 was significantly related to metastasis and prognosis in patients with hepatocellular carcinoma (HCC)." (PMID 37497410, 2023). "In vitro and in vivo studies have shown that CALB2 promotes hepatocellular carcinoma metastasis via the TRPV2-Ca2+-ERK1/2 signaling pathway." (PMID 35836930, 2022). "Calbindin 2 (CALB2) promotes metastasis of hepatocellular carcinoma." (PMID 36249071, 2022).
breast carcinoma (4 papers, 2011 to 2023). "High CALB2 levels were also associated with better overall survival in a breast cancer cohort treated with tamoxifen and radiotherapy (p = 0.0322)." (PMID 21629658, 2011). "While high CALB2 or PDPN expression in several other carcinomas, including breast cancer, was associated with a poor prognosis, the OS of other cancers, in particular hematologic malignancies, showed the opposite association." (PMID 32533757, 2020). "The association between CALB2 expression and patient survival was also examined in the GSE9893 breast cancer dataset (PMID: 18347175)." (PMID 21629658, 2011).
schizophrenia (4 papers, 2021 to 2024). A major psychotic disorder characterized by abnormalities in the perception or expression of reality. "Moreover, Calb2 has been associated with other neurological disorders including schizophrenia." (PMID 34078425, 2021). "Enrichment of schizophrenia genetic liability was also observed in genes with high expression specificity for calretinin (CALB2)-positive subpopulations of developing GABAergic neurons from the CGE." (PMID 38869145, 2024). "Prior studies show that both of these genes show increased expression in schizophrenia patients’ brains compared to controls; Mef2c in the prefrontal cortex and Calb2 in the dentate gyrus." (PMID 35941129, 2022).
malignant mesothelioma (3 papers, 2018 to 2024). A malignant neoplasm of the pleura or peritoneum, arising from mesothelial cells. "The mechanisms of CALB2 in malignant mesothelioma is through the binding of septin 7 on CALB2 promoter." (PMID 35963640, 2022). "The calcium-binding protein calretinin (gene name: CALB2) is currently considered as the most sensitive and specific marker for the diagnosis of malignant mesothelioma (MM)." (PMID 29699512, 2018). "Additionally, CALB2 is currently considered as the most sensitive and specific marker for the diagnosis of malignant mesothelioma." (PMID 35963640, 2022). "Tissue CALB2 is clinically used to distinguish CALB2-positive epithelioid and mixed-type (biphasic) malignant mesothelioma (MM) from adenocarcinoma, while serum CALB2 could potentially serve as a predictive biomarker for poor survival and outcomes of cisplatin-based chemotherapy in MM." (PMID 39358777, 2024).
ischemic stroke (2 papers, 2015 to 2020). A stroke disorder caused by obstruction of blood flow to the brain, due to thrombotic (local blood clot formation) or embolic (due to a blood clot or other material traveling from another site) event. "Proteomics analysis in a global ischemic stroke also found that Calb2 associated with endoplasmic reticulum stress-induced neuronal cell apoptosis." (PMID 32632112, 2020). "After an ischemic stroke, one protein spot, namely the calretinin (CALB2) protein, showed increased expression." (PMID 26016499, 2015). "Proteomic analysis suggested that the differential expression of CALB2 during a global ischemic stroke could be involved in the mechanisms of ER stress-induced neuronal cell apoptosis, which occurred via IRE1-alpha/TRAF2 complex formation, with activation of JNK1/2 and p38 MAPK." (PMID 26016499, 2015).
pancreatic cancer (2 papers, 2023 to 2024). "Due to the difficulty to detect and quantify the migration of organoids, we then indirectly co-cultured human primary pancreatic cancer cell lines with CALB2-OE PSCs to investigate the impact of CALB2+ CAFs on cancer cell migration." (PMID 39358777, 2024). "However, the roles of CALB2 in pancreatic cancer cells and CAFs remain largely elusive." (PMID 39358777, 2024).
cognitive deficits (1 paper, 2022). "To explore the molecular mechanisms underlying mossy cell‐hTau N368‐induced cognitive deficits, we carried out mossy cell RNA‐Seq analysis after mossy cell‐specific overexpressing hTau N368 in Calb2‐Cre mice." (PMID 35355405, 2022).
colorectal adenocarcinoma (1 paper, 2026). The most common type of colorectal carcinoma. "Functional experiments demonstrated that CALB2 expression accelerated tumor growth in vivo and promoted the migration and proliferation of colorectal adenocarcinoma cells in vitro." (PMID 42194967, 2026).
Glucose intolerance (1 paper, 2026). Glucose intolerance (GI) can be defined as dysglycemia that comprises both prediabetes and diabetes. "The predictor variables can be considered in three groups: those with insulin and glucose intolerance (Mbd2, Tnip1, Itgb4, and Iffo2), those with BMR (1010001N08RiK and Clvs2), and those associated with Tb (Calb2)." (PMID 41432313, 2026).
lung carcinoma (1 paper, 2009). "In the Lung Cancer dataset, we succeeded in identifying highly discriminative genes (e.g., CALB2, HAS1, and ANXA8) implicated in the pathogenesis of MPM, ADCA, or other tumors." (PMID 19874631, 2009).
meningioma (1 paper, 2016). A generally slow growing tumor attached to the dura mater. "Autosomal genes that were comparably lower expressed in meningiomas from females included EPH receptor A3 (EPHA3), parvalbumin (PVALB), calbindin 2 (CALB2), and solute carrier family 38 member 3 (SLC38A3)." (PMID 27096627, 2016).
neuroblastoma (1 paper, 2011). Neuroblastoma (NB) is the most common solid, extracranial childhood tumor. "A follow-on study using an N18-RE 105 neuroblastoma-retina hybrid model, demonstrated that cells stably transfected with CALB2 cDNA were protected from Ca2+-dependent L-glutamate-induced cytotoxicity." (PMID 21629658, 2011).
neuronal ceroid lipofuscinosis type 2 (1 paper, 2021). "However, one specific protein detected in both human and mouse CSF, namely CALB2, was significantly elevated in both the proteomics analysis and was confirmed by ELISA, similar to that observed in late infantile neuronal ceroid lipofuscinosis type 2 (CLN2) and CLN3 patients." (PMID 33478506, 2021).
Niemann-Pick disease (1 paper, 2025). A group of inherited, severe metabolic disorders in which sphingomyelin accumulates in lysosomes in cells. "CALB2, a calcium-binding protein highly expressed in neurons, has previously been found elevated in CSF from individuals with Niemann-Pick disease, along with NEFL and tau55–57, suggesting a potential association to neuronal damage." (PMID 39753643, 2025).
retinal (1 paper, 2023). "Our data indicate that neuronal A2 expression is neurotoxic after injury, and A2 deletion in Calb2 expressing neurons limits ONC-induced retinal neurodegeneration and improves visual function." (PMID 37816735, 2023).
varicocele (1 paper, 2023). A condition characterized by the dilated tortuous veins of the spermatic cord with a marked left-sided predominance. "The present study compared seminal calbindin 2 (CALB 2) levels and semen parameters in men with and without varicocele." (PMID 37067726, 2023).
tumor (19 papers, 2011 to 2026). "Calbindin 2 (CALB2), a calcium-binding protein, has been implicated in tumor progression in several malignancies, but the precise functional involvement of this molecule in COAD remains insufficiently characterized." (PMID 42194967, 2026). "Our larger human PDAC tissue microarray cohort confirmed that CALB2 is not only a tumor-specific but also a CAF-associated poor prognostic marker, indicating that CALB2 might also exert biological effects on CAFs." (PMID 39358777, 2024). "CALB2 was overexpressed in tumor stromal CAFs, where the mean density of IHC showed a strong positive correlation between CALB2 and fibroblast activation protein (FAP)." (PMID 39358777, 2024). "Next, we evaluated CALB2 expression in tumor tissues surgically resected from 36 PDAC patients and its relationship with TME changes using immunohistochemistry (IHC)." (PMID 39358777, 2024). "Pancreatic transplantation of organoids in NPG mice (PDOX model) further demonstrated that CALB2+ CAFs promote tumor growth in vivo." (PMID 39358777, 2024). "A total of five ST spot clusters were annotated to tumour cells (marked by relatively high expression of CALB2)." (PMID 38318640, 2024). "Consistently, both the RNA and protein abundance of CALB2 was significantly higher in tumor tissues compared to normal adjacent tissues in multiple PDAC datasets." (PMID 39358777, 2024). "Herein, we found that CALB2 is specifically expressed in both CAFs and cancer cells within the tumor tissue using human PDAC scRNA-seq analysis." (PMID 39358777, 2024). "Compared to the control, CALB2+ CAFs significantly promoted cancer cell proliferation and tumor growth in vivo." (PMID 39358777, 2024). "Proteomic analysis of laser-capture microdissected PDAC samples revealed that CALB2 serves as a compartment-specific poor prognostic marker for the tumor area." (PMID 39358777, 2024). "CALB2 expression was significantly higher in stage III/IV CRC tissues than in stage I/II tissues, indicating a connection between CALB2 and tumor metastasis." (PMID 37497410, 2023). "Our immunohistochemistry (IHC) results revealed that CALB2 exhibited relevant stronger staining in two cases of tumor (2/16), with the other 14 cases displaying low expression (14/16)." (PMID 35836930, 2022). "Intriguingly, high CALB2 or PDPN expression was strongly associated with a poor clinical outcome, and calretinin expression was observed at the invasive tumor edges of HGSC metastases." (PMID 32533757, 2020). "In addition to serving as a biomarker for malignancy, CALB2 also plays a vital role in tumor metastasis." (PMID 39358777, 2024). "In addition to CAFs, CALB2 was also highly expressed in malignant ductal cells within the tumor tissue." (PMID 39358777, 2024). "Given that PDAC cells utilize an EMT program during metastatic dissemination, and the proportion of CALB2+ cancer cells was significantly higher in the tumor with metastasis in our cohort, we preliminarily assumed that CALB2 facilitated PDAC metastasis in vivo." (PMID 39358777, 2024). "In this study, we confirmed that CALB2 is significantly higher in tumor with metastasis using human PDAC tissue microarray, and it promotes malignant phenotypes, especially metastatic growth through loss of function in human metastatic PDAC cells or gain of function in primary PDAC cells." (PMID 39358777, 2024). "Analysis of tumor samples confirmed that the expression profile of the three transcripts observed in cell lines reflects splicing events that are also present in tumors, with the full-length CALB2 being in all cases the most abundant transcript." (PMID 28611824, 2017). "Therefore, this study demonstrated that CALB2 can collaborate with hypoxia to promote iCAF activation and CALB2-activated CAFs play a tumor-promoting role in PDAC progression, which enhances our understanding of the molecular and functional heterogeneity of CAFs." (PMID 39358777, 2024).